RUNX2 (RUNX family transcription factor 2)
Diseases named in the same sentence as RUNX2 in open-access papers (continued):
Sharing a sentence is not in itself a finding about the gene and the disease.
osteosarcoma (continued). "Importantly, p27KIP1 is lost in differentiated osteosarcoma, driving cell cycle exit and normal bone development upon Runx2-mediated activation." (PMID 33809018, 2021). "Given the contribution of Runx2 and downstream factors to osteosarcomagenesis and bone development, it is therefore consistent that elevated Runx2 expression has been correlated with significantly poorer outcomes in osteosarcoma." (PMID 33809018, 2021). "Runx2 has been shown to physically interact with and be regulated by Rb and Myc, further demonstrating the complicated interactions that drive dysregulation of normal development into osteosarcoma." (PMID 33809018, 2021). "Of note, RUNX2 expression is frequently elevated in osteosarcoma." (PMID 34831147, 2021). "Only one gene (RUNX2) out of nine was significantly downregulated by all the three treatments; it is possible that RUNX2 could be a potent therapeutic target in osteosarcoma treatment." (PMID 32695811, 2020). "RUNX2, another marker involved in osteosarcoma, was examined." (PMID 32695811, 2020). "Furthermore, Runx2 suppressed the proliferation of cells with osteogenic potential and osteosarcoma cells, and the introduction of siRNA against Runx2 into human mesenchymal stem cells increased their proliferation." (PMID 30987410, 2019). "Additionally, in miR-302b-overexpressing and miR-302b-downregulated osteosarcoma cells, the mRNA and protein levels of Runx2 were inhibited and promoted, respectively." (PMID 29042587, 2017). "Furthermore, miR-302b functions as a tumour repressor in the invasion and migration activity of osteosarcoma by downregulating Runx2." (PMID 29042587, 2017). "We confirmed that WWOX inhibited RUNX2 expression in osteosarcoma cells." (PMID 28977834, 2017). "Taken together, our results indicate that miR-302b functions as a tumour repressor in the invasion and migration of osteosarcoma by directly downregulating Runx2 expression and may be a potential therapeutic target for osteosarcoma." (PMID 29042587, 2017). "Furthermore, in osteosarcoma, Runx2 is also targeted by several miRNAs including miR-34c28, miR-20529, miR-30a30, miR-23a31." (PMID 29042587, 2017). "These genetic studies suggest that Runx2 may play a critical role in osteosarcoma oncogenesis on account of its significant function in regulating osteoblast differentiation and cell invasion and migration." (PMID 29042587, 2017). "Previous studies have shown that Runx2 is highly expressed in osteoblasts and osteosarcoma cells." (PMID 27512956, 2016). "In addition, genomic promoter occupancy of RUNX2 in osteosarcoma cells identifies genes involved in motility, such as FAK/PTK2 or talin (TNL1)." (PMID 26204939, 2015). "Over expression of Smad 5 increases RUNX2 levels in human MG63 osteosarcoma cells." (PMID 22966907, 2012). "RUNX2 expression has also been detected in most osteosarcoma primary tumors." (PMID 23133552, 2012). "RUNX2 is frequently amplified and over-expressed in osteosarcomas, and may play an important role in osteosarcoma tumourigenesis." (PMID 23144859, 2012). "In our lab, we have detected amplification-related overexpression of the RUNX2 gene in a subset of osteosarcoma tumours and identified a correlation between high RUNX2 mRNA overexpression and poor tumour response to chemotherapy based on the percentage of tumour necrosis following treatment." (PMID 21197465, 2011). "Furthermore, RUNX2 protein levels appear to be selectively deregulated in several osteosarcoma-derived cell culture models." (PMID 21197465, 2011). "Additionally, larger cohorts of patients are necessary to definitively link RUNX2 level to treatment response in osteosarcoma tumours." (PMID 21197465, 2011).
osteosarcoma (continued). "In addition, it has been reported that Runx2 induces Bax expression in osteosarcoma cells by binding to regulatory domain on the human Bax promoter." (PMID 24250365, 2011). "An association has been found between upregulated Notch signaling and lung metastatic potential in osteosarcoma cell lines, but no functional studies have yet linked inactivation of RUNX2 directly to osteosarcoma metastasis." (PMID 21197465, 2011). "Speculation has reigned over the consideration that Runx2, the definitional preosteoblast transcription factor, functions as a tumor suppressor gene in osteosarcoma." (PMID 21403899, 2011). "The instability of chromosome 6p12-p21 that leads to RUNX2 gain and amplification has been demonstrated by many studies of patient samples, including biopsies, and thus it is probably an early event in osteosarcoma pathogenesis." (PMID 21197465, 2011). "This explains the dysfunctional presence of Runx2 in human osteosarcomas." (PMID 21403899, 2011). "RUNX2 is often overexpressed in osteosarcoma, and so its normal functions may also be important for the development of the tumor." (PMID 21772794, 2011). "RUNX2 levels are deregulated in osteosarcoma and chondrosarcoma cells." (PMID 21029421, 2010). "RUNX2 was one of the genes overexpressed in our set of tissue samples, and the only gene whose overexpression was significantly related to poor response to chemotherapy in osteosarcomas." (PMID 20465837, 2010). "In addition to being overexpressed in osteosarcoma tumor samples relative to normal osteoblasts, RUNX2 was the only gene of the 16 to show significant overexpression in tumors that had a poor response to chemotherapy relative to good responders." (PMID 20465837, 2010). "Therefore, RUNX2 is also a known marker of chemoresistance in osteosarcoma." (PMID 40806771, 2025). "However, further validation is needed to determine whether the increased osteogenic differentiation in osteosarcoma cells resulting from ITGB3-KD-mediated activation of the JNK/c-JUN/RUNX2 pathway directly regulates apoptosis in osteosarcoma cells." (PMID 40410897, 2025). "Given RUNX2’s involvement in transcriptional networks associated with metabolism and tumor progression, it may serve as an upstream regulator of MAEA or its related pathways, thereby modulating chemotherapy resistance in tumors such as osteosarcoma." (PMID 40989695, 2025). "However, in osteosarcoma, RUNX2 has been found to be dysregulated and abruptly expressed." (PMID 40806771, 2025). "Thus, RUNX2 is considered a potential candidate for targeted therapy of osteosarcoma." (PMID 40806771, 2025). "Based on our previous work and current research status, we consider that the abnormally elevated expression of circ_0001722 in Osteosarcoma cells may participate in the proliferation and invasion of Osteosarcoma by affecting the expression of miR-204-5p and Runx2." (PMID 37453970, 2023). "However, no functional investigations have yet connected the inactivation of RUNX2 directly to osteosarcoma metastasis, despite the fact that there is a connection between increased Notch signaling and lung metastatic capabilities in osteosarcoma cell lines." (PMID 37370857, 2023). "RUNX2 combined with osteopontin may serve as a new predictive biomarker in resected osteosarcoma." (PMID 36289596, 2022). "Otherwise, one study showed that the growth suppressive activity of Runx2 was normally inactivated in part by protein destabilization, which permited cell cycle progression beyond the G1/S phase transition, and Runx2 was upregulated again after mitosis in human osteosarcoma cells." (PMID 33767130, 2021). "Finally, it was reported that enforcing the expression of the tyrosine kinase receptor c-met into primary cultures of human bone-derived cells converts them into osteosarcoma cells and leads to an increase in the expression of several osteoblastic differentiation markers such as RUNX2 and Osterix." (PMID 32230926, 2020).
osteosarcoma (continued). "Therefore, in osteosarcoma cells, RUNX2 could stimulate the PI3K/AKT pathway through the positive regulation of FAK." (PMID 26204939, 2015). "Our study also corroborates an expanding body of evidence showing that RUNX2, a transcription factor central to the control of osteoblast differentiation during skeletal development and remodelling, is frequently expressed at high levels in osteosarcoma biopsies." (PMID 24835790, 2014). "In normal osteoblasts, RUNX2 mRNA and protein levels are elevated in quiescent cells upon growth factor deprivation, but this growth-related regulation of RUNX2 gene expression is perturbed in several osteosarcoma cell types that express RUNX2 at elevated levels." (PMID 21029421, 2010). "In the context of oncogenic signaling, the reciprocal activation between RUNX2 and the PI3K/AKT pathway has been recognized as a pivotal factor in driving tumor progression and fostering chemoresistance in osteosarcoma." (PMID 40332124, 2025). "The findings suggest that ITGB3-KD enhances the radiosensitivity of osteosarcoma cells by promoting osteogenic differentiation and apoptosis via activation of the JNK/c-JUN/RUNX2 signaling pathway." (PMID 40410897, 2025). "We propose that RUNX2 and HIF-1α complement each other in osteosarcoma progression through molecular crosstalk." (PMID 40806771, 2025). "In osteosarcoma, upregulation of MMP-2, MMP-9, and MMP-13 has been observed in the presence of RUNX2, which promotes metastasis and invasion." (PMID 40806771, 2025). "Quantitative assessment of osteogenic markers (RUNX2, OCN, and OPN) confirmed that ITGB3-KD drives osteogenic differentiation in osteosarcoma." (PMID 40410897, 2025). "Taken together, these findings indicate that ITGB3-KD exerts radiosensitizing effects on osteosarcoma cells by promoting osteogenic differentiation and apoptosis through activation of the JNK/c-JUN/RUNX2 pathway." (PMID 40410897, 2025). "In osteosarcoma, GCN5 induces H3K27 acetylation at the Runx2 promoter, upregulating Runx2 transcription and promoting pulmonary metastasis." (PMID 40761481, 2025). "the reciprocal activation between RUNX2 and the PI3K/AKT pathway has been recognized as a pivotal factor in driving tumor progression and fostering chemoresistance in osteosarcoma." (PMID 40332124, 2025). "These western blot findings suggested that ITGB3-KD enhanced osteogenic differentiation in osteosarcoma by activating the JNK/c-JUN pathway, with RUNX2 serving as the major downstream molecule mediating this effect." (PMID 40410897, 2025). "Promoted bone morphogenic protein 2, induced osteogenic differentiation under NIR, alkaline phosphatase activity, increased expression of Col, RUNX2, BSP bone-related genes and C2C12 myoblast cells, osteosarcoma cell death, inhibited tumor growth." (PMID 38791452, 2024). "Seventeen cases of canine osteosarcoma (13 EOS and 4 SOS) were retrospectively selected and submitted to immunohistochemistry for RUNX2 and Karyopherin alpha-2." (PMID 38362297, 2024). "The osteosarcoma cell line SAOS-2 is able to upregulate BAX expression and induce apoptosis thanks to RUNX2 being triggered by BMP/SMAD signaling." (PMID 37370857, 2023). "•The datasets present the effects of RUNX2 silencing on the gene expression pattern and metabolite profile in SJSA-1 osteosarcoma cells." (PMID 37663774, 2023). "In osteosarcoma, tumor cell invasion and migration were triggered by lncRNA HCG18 via the repression of miR-34a, a negative regulator of RUNX2, which increased RUNX2 levels." (PMID 37108164, 2023). "While inhibiting the metastasis of colon cancer by recruiting histone deacetylase 3 (HDAC3) to the Runx2 promoter, CBX4 promotes the metastasis of osteosarcoma by recruiting GCN5, which catalyzes H3K27 acetylation of the Runx2 promoter." (PMID 37691307, 2023).
osteosarcoma (continued). "In conclusion, this study suggested that the miRNAs including miR-22-3p, miR-154-5p, miR-34a-5p, miR-485-3p, miR-93-5p, and miR-9-5p and the genes including LEF1, RUNX2, CSF1R, CDKN1A, and FBN1 act as key factors in the progression of osteosarcoma." (PMID 35340229, 2022). "In summary, this study suggests the miRNAs including miR-22-3p, miR-154-5p, miR-34a-5p, miR-485-3p, miR-93-5p, and miR-9-5p and the genes including LEF1, RUNX2, CSF1R, CDKN1A, and FBN1 are the key factors in the progression of osteosarcoma." (PMID 35340229, 2022). "In human osteosarcoma cells (MG63 cells), the expression of Runx2 was concurrently increased with Dlx5, Mage-D1 and Necdin41." (PMID 36585447, 2022). "From osteoblasts to osteosarcoma, SOX9, SPP1 (osteopontin) and RUNX2 were also considered as origin-related factors." (PMID 34828292, 2021). "CBX4 is known to recruit GCN5 to the Runx2 promoter to transcriptionally upregulate Runx2; in this manner, CBX4 can promote the metastasis of osteosarcoma." (PMID 34046352, 2021). "The direct interaction between miR-34c and RUNX2-mRNA was further supported by Van der Deen’s work on an osteosarcoma model, in which the weak expression level of this miRNA in SaOS-2 and U2OS osteosarcoma cell lines was also reported." (PMID 32230926, 2020). "It was shown that 20 dynes/cm2 shear force inhibits the mRNA expressions of Runx2 and OCN in human MG63 osteosarcoma cells after 8 and 24 h of stimulations." (PMID 32630668, 2020). "Therefore, we were curious whether CBX4 could also affect Runx2 transcription in osteosarcoma." (PMID 32111827, 2020). "Triggered expression of RUNX2 by Wnt/B-catenin signaling was shown to promote the expression of several genes such as MMP1 and MMP2 that promote cell migration and metastasis in osteosarcoma by remodeling the extracellular matrix." (PMID 32695811, 2020). "In osteosarcoma, NNT-AS1 can sponge miR-320a and up-regulate the expression of β-catenin, RUNX2, p-AKT, insulin-like growth factor type 1 receptor (IGF1R), MYC, cyclin D1, and MMP-13, thereby promoting osteosarcoma cell growth and tumor development." (PMID 33113895, 2020). "It is well known that abnormal expression of RUNX2, ALPL, and BGLAP determines impaired molecular and cellular functions in Mg-63 and Saos-2, but this phenomenon is different in the two osteosarcoma cell lines." (PMID 31236409, 2019). "Among transcription factors that were able to regulate OPN expression, RUNX2 was earlier reported to modulate the expression and secretion levels of OPN proteins in osteosarcoma cells." (PMID 31832019, 2019). "RUNX2 was reported to modulate expression and secretion of the OPN in osteosarcoma cells to promote adhesion to endothelial pulmonary cells and lung metastasis." (PMID 31832019, 2019). "WWOX promoted apoptosis and inhibited invasion and expression of bcl-2, OPN, RUNX2, and VEGF in osteosarcoma cells in vitro." (PMID 28977834, 2017). "Here, we found that WWOX inhibited the expression of RUNX2, bcl-2, OPN, and VEGF in osteosarcoma cells." (PMID 28977834, 2017). "In this study, we investigated the role of WWOX in angiogenesis in human osteosarcoma and its effects on the expression of CD34, RUNX2, and VEGF to understand their potential interaction in the development of osteosarcoma." (PMID 28977834, 2017). "Together, these results suggest that reduced WWOX expression in osteosarcoma cells inhibited apoptosis, promoted invasion, upregulated bcl-2, OPN, RUNX2, and VEGF expression, and increased microvessel density (MVD)." (PMID 28977834, 2017). "In conclusion, we found that the inhibition of WWOX expression, which was due at least in part to DNA methylation, inhibited apoptosis, promoted invasion, upregulated bcl-2, OPN, RUNX2, and VEGF expression, and increased MVD in osteosarcoma cells." (PMID 28977834, 2017). "Several targets of miR-23a were previously validated in other tumor cell types, including RUNX2 and CXCL12 in osteosarcoma." (PMID 27601936, 2016).
osteosarcoma (continued). "In a first study, human osteosarcoma MG63 cells, exhibiting an immature phenotype reminiscent of MSCs,34 were used to assess the biological effect of DLX5 or RUNX2 mRNA transfer." (PMID 26528487, 2015). "In line with the recent demonstration that CD99-restored expression in osteosarcoma cell correlated with ERK 1/2, RUNX2, and AP-1 activation, we here show that PI3K and ERK1 K inhibitors rescue COLLI, RUNX2 and JUND OB protein levels." (PMID 26000312, 2015). "In converse to the finding that RUNX2 upregulates BAX expression in the SAOS-2 cell line, nitric oxide (NO) treatment of the MG-63 osteosarcoma cell line induces RUNX2-mediated BCL2 expression, which promotes survival of the cells during oxidative stress." (PMID 21197465, 2011). "However, RUNX2 destabilization is compromised in several osteosarcoma cell types that express constitutively high levels of RUNX2, suggesting that bone cancer cells may bypass the growth suppressive properties of RUNX2." (PMID 21029421, 2010). "The well-documented WWOX-RUNX2 axis in osteosarcoma, demonstrated by WWOX’s ability to suppress RUNX2-driven metastasis, raises the possibility that similar mechanisms might be at play in ES." (PMID 41141138, 2025). "Studies have shown that AST significantly reduced the cell proliferation of 3 canine osteosarcoma cell lines, OS 2.4, HMPOS, and D17, by up-regulating the expression of Runx2, type I collagen, osteopontin, and osteocalcin in MG63 cells, and inhibited the mitotic activity of osteosarcoma cells." (PMID 41346414, 2025). "In osteosarcoma, CBX4 has been shown to enhance tumorigenesis by activating HIF1α signaling and by recruiting the histone acetyltransferase general control nonderepressible 5 (GCN5) to upregulate runt-related transcription factor 2 (Runx2)." (PMID 41502529, 2025). "Therefore, this review focuses on the role of RUNX2 and HIF-1α in the alteration of the tumour microenvironment, which further promotes angiogenesis, metastasis, and resistance to therapy in osteosarcoma." (PMID 40806771, 2025). "Moreover, frequent amplification of the RUNX2 gene in osteosarcoma cell lines correlates with elevated RUNX2 levels, subsequently initiating MYC transcription and driving osteosarcoma tumorigenesis and progression." (PMID 38430423, 2024). "Therefore, as schematized in the diagram, FBXW11, acting on beta‐catenin, indirectly reduces RUNX2 levels in osteosarcoma cells, whose FBXW11 levels decrease following miR 221 overexpression, increased levels of both beta‐catenin and RUNX2 are observed." (PMID 37199076, 2023). "Our results suggest that the silencing of ANAPC1 affects the expression level of RUNX2 in human osteosarcoma cells, but the mineralisation process is not hindered." (PMID 37629076, 2023). "Vincristine, dexamethasone, and vinblastine may form a promising drug–target pair with RUNX2, OMD, and CD4 for Osteosarcoma treatment." (PMID 36686663, 2022). "Thus, this study suggests that the hub nodes LEF1, RUNX2, CSF1R, VAV3, FZD3, CDKN1A, and FBN1 are key factors in the progression of osteosarcoma." (PMID 35340229, 2022). "The inhibitory effects of ML264 on osteosarcoma cells are likely mediated via inhibition of JAK2 and STAT3 phosphorylation, decrease in β‐catenin and Runx2 levels, down‐regulation of cyclin D1, cyclin E1, CDK4, N‐cadherin, vimentin, Snail and MMPs expression, and up‐regulation of E‐cadherin levels." (PMID 32285603, 2020). "Moreover, cells transfected with PPARδ- or SCD-1-specific siRNA to knockdown the corresponding gene expression significantly recovered the inhibitory effect of 20 dynes/cm2 shear force on Runx2 and OCN mRNA expressions in human MG63 osteosarcoma cells." (PMID 32630668, 2020).